BAD (BCL2 associated agonist of cell death)
Diseases named in the same sentence as BAD in open-access papers (continued):
Sharing a sentence is not in itself a finding about the gene and the disease.
tumor (continued). "Both gain- and loss-of-function analyses revealed that GOLGA2P10 conferred tumor cells with resistance to ER stress-induced apoptosis by increasing the protein level of BCL-xL and promoting phosphorylation of BAD." (PMID 32332695, 2020). "Altogether, these results indicate BAD expression increases tumor volume, however, these cells are more sensitive to docetaxel treatment with enhanced cell death and decreased tumor size." (PMID 31942016, 2020). "Since phosphorylation of S118 regulates binding to Bcl-XL and apoptotic and metabolic activities of BAD, we directly tested the contribution of S118 phosphorylation on cell and tumor growth." (PMID 30635657, 2019). "Immunohistochemistry was used to determine the relative expression levels of phospho-BAD isoforms in tumour samples." (PMID 31767884, 2019). "In summary, our data demonstrated that BAD increased cellular accumulation resulting in increased tumor volume." (PMID 30635657, 2019). "In vivo, in a zebrafish xenograft model, BAd significantly increased angiogenesis at the primary tumor site and enhanced the dissemination of BCC." (PMID 30105032, 2018). "PIM2 promotes tumor survival mainly through phosphorylation of the pro-apoptotic BH3-only protein BAD, as well as through regulation of MYC activity, and Cap-dependent protein translation." (PMID 28561737, 2017). "The results showed that OTUD7B, TNIP2 and BAD, which are closely correlated with cell survival and apoptosis progression in tumours, were three putative targets of miR-1180." (PMID 26928365, 2016). "In particular, in silenced MCF-7 cells we found a higher levels of well-known pro-apoptotic factors such as BAD and Caspase-9 and of Col18, that acts as an endogenous inhibitor of tumor growth and angiogenesis." (PMID 26799588, 2016). "Over-expression of BCL-XL or knock down of BAX, BIM, BAD or apoptosis inducing factor (AIF) protected tumor cells." (PMID 26981780, 2016). "Stimulated by growth factors EGF and HGF respectively, EGFR/Ras/Raf/MEK/ERK and HGFR/PI3K/AKT pathways converge to phosphorylate BAD that plays a critical anti-apoptotic role in many types of tumor cells." (PMID 27590512, 2016). "For example, BCL2-associated agonist of cell death (BAD) functions as a shared target of Akt and ERK signaling in phosphatase and tensin homolog (PTEN) deficient tumor cells." (PMID 26848623, 2016). "Inhibition of AXL reversed chemoresistance by decreasing expression of the anti-apoptotic proteins BCL-2, BCL-XL, MCL1 and survivin in tumor cells and activated pro-apoptotic proteins BAD, BAX, BCL-2, BAK and PUMA." (PMID 26328272, 2015). "In xenograft tumor tissues, the expression levels of BAD were increased in overexpression groups compared with H1299/SPC-A1 and H1299/SPC-A1-NC cell groups." (PMID 23725574, 2013). "Nevertheless, BAD overexpression in H1299/SPC-A1 cells reduced tumor formation compared with H1299/SPC-A1 and H1299/SPC-A1-NC control (all p < 0.01)." (PMID 23725574, 2013). "Through the regulation of translation or by directly influencing the activity of p70S6K, mTOR can induce the antiapoptotic functions of mitochondrial proteins, e.g. by BAD phosphorylation, supporting the survival and proliferation of tumor cells." (PMID 23693095, 2013). "Further immunohistochemical analysis showed that xenograft tumor with BAD overexpression had a decreased number of cells that stained positive for the proliferative marker Ki-67." (PMID 23725574, 2013). "These suggested that, in NSCLC, BAD inhibited cell proliferation in vitro and tumor growth in vivo through direct induction of apoptosis without affecting cell cycle progression." (PMID 23725574, 2013). "In the tumour cells which BCL-2(-)BAD(+) the chemosensitivity to the 4 drugs are higher than the BCL-2(+)BAD(+)and BCL-2(+)BAD(-)ones." (PMID 20691103, 2010). "When dephosphorylated, BAD promotes apoptosis, while in a phosphorylated form it stimulates proliferation and tumor growth in vivo." (PMID 19593445, 2009).
tumor (continued). "C4-2Luc xenografts with a reduced expression of BAD showed reduced tumor take and grew at a slower rate than cells with intact BAD expression." (PMID 19593445, 2009). "BAD staining showed a lower median H-Score on normal tissues than primary neoplastic or locally metastatic tumors, i.e., a 100 median H-Score for normal colonic mucosa, 140 for LN tumor metastasis (p = NS), 170 for TC (p = 0.003), and 190 for IF (p = 0.001)." (PMID 41514585, 2025). "As a pro-apoptotic molecule, increased phosphorylation of BAD can enhance tumor cell apoptosis." (PMID 40958869, 2025). "We also observed increased BAD expression in primary tumors compared to normal tissue, both at the tumor center and invasive margin, while a difference was found, but without being statistically significant, between its expression in LN metastases and the normal intestinal epithelium." (PMID 41514585, 2025). "scRNA-Seq data showed that tumor-promoting genes associated with cell proliferation, stemness, metastasis, drug resistance, and key transcription factors (TFs) were upregulated in OX40+ ECs from CRC tissues, whereas important tumor suppressors, including RB, BAD, and FAS, were markedly reduced." (PMID 40026246, 2025). "This not only impaired tumor cell proliferation under hypoxic conditions but may also increase their susceptibility to apoptosis by reducing the activation of BAX and BAD proteins." (PMID 39031012, 2024). "BAD upregulation via activated AR may assume a significant relevance, as tumor-suppressor potential has been reported for several BH3-only proteins, consistently with their pro-apoptotic role." (PMID 37686282, 2023). "Studies have also found that BAD expression promotes tumor-cell growth." (PMID 37674118, 2023). "High expression of BAD is closely related to tumor cell apoptosis." (PMID 36313628, 2022). "We found that TCS/GrzB combination treatment markedly enhanced the expression of BAD in tumor tissues compared with its expression in the other treatment groups, suggesting that TCS/GrzB might suppress tumor growth and progression by upregulating BAD." (PMID 33750370, 2021). "BAD phosphorylation has recently been reported to promote tumour cell survival, and post‐translational modification might therefore contribute to impaired pro‐apoptotic proteins." (PMID 32419250, 2020). "BAD phosphorylation drove cellular growth and tumor aggressiveness." (PMID 30635657, 2019). "TNBC tumours were enriched for the expression of phospho-BAD isoforms." (PMID 31767884, 2019). "Wild-type BAD stimulated cell and tumor growth that was driven by different pathways than S118D." (PMID 30635657, 2019). "BAD-S118D-expressing tumors had significantly increased Ki67-positive and CD-31 positive cells, supporting that increased proliferation and angiogenesis contributed to tumor growth." (PMID 30635657, 2019). "This particular feature of BAD-LAMP seems to be exploited in tumour infiltrating pDCs, since higher expression of BAD-LAMP in pDCs exposed to tumour microenvironments contribute to their functional impairment and incapacity to produce type-I IFN, both associated with poor prognosis." (PMID 29030552, 2017). "Taken together, these results again underline the importance of BAD-LAMP expression in controlling TLR9 signalling and suggest that its reinforced expression in tumour-associated pDCs contributes to their immunomodulatory phenotypes by decreasing the type-I IFN production capacity." (PMID 29030552, 2017). "Upregulation of AKT substrates (e.g., inhibition of BAD [pS136]) also suggested reciprocal signaling might protect tumor cells from apoptosis." (PMID 27087446, 2016). "However, only inhibiting the two pathways simultaneously can activate BAD and induce apoptosis in tumor cells." (PMID 26848623, 2016). "One of the substrates of PIM3 is the tumor suppresser gene pro-apoptotic BCL2 family member BAD." (PMID 26039373, 2015).
tumor (continued). "However, also in these tumor sublines, CX− cells with the lower mHsp70 expression showed an increased expression in Caspase 3/7, BAD and BAX compared to CX+ cells." (PMID 26197988, 2015). "As the significant changes of Akt, mTOR, and BAD along with the progression of tumor grades I to III, it may correlate with the increasing number of lipid rafts." (PMID 25243186, 2014). "Moreover, the expression of BAD phosphorylation was significantly reduced along with the progression of tumor grades I to III." (PMID 25243186, 2014). "In this study, our data provided experimental evidence that BAD could play functions as a tumor suppressor in NSCLC." (PMID 23725574, 2013). "In the further investigation, BAD may function as tumor suppressor regulating cell growth and apoptosis in the development of NSCLC, and is a potential target for tumor intervention." (PMID 23725574, 2013). "All data suggested BAD overexpression significantly enhanced tumor cell apoptosis." (PMID 23725574, 2013). "Thus, BAD phosphorylation appears to be a useful biomarker to predict the anti-tumor efficacy of PI3K inhibitors." (PMID 24040284, 2013). "Regardless of the exact mechanism that permits BAD to stimulate tumor growth, this capacity may provide selective pressure to increase BAD expression in tumors." (PMID 19593445, 2009). "However, further investigations will have to clarify the exact role of BAD in gefitinib-induced apoptosis of NE tumour cells." (PMID 14583782, 2003). "Therefore, promoting BAD expression has attracted more and more attention in tumor treatment." (PMID 36313628, 2022). "This shift in prooxidant enzyme and antioxidant enzyme balance may cause the imbalance of proapoptotic (BAX and BAD) and antiapoptotic genes (BCL2 and BCL2L1), resulting in a tumor microenvironment which is in favor of surviving and resistant to apoptosis in Tg tumor." (PMID 33456675, 2020). "We next tested whether BAD also regulated growth in a tumor-bearing model." (PMID 30635657, 2019). "Therefore, in addition to regulating apoptosis, BAD might be involved in various cellular functions, such as proliferation and tumor growth in NSCLC." (PMID 23725574, 2013). "In light of these findings, tumor therapy with BAD protein up-regulation may be warranted." (PMID 23725574, 2013). "Thus, kinases that phosphorylate BAD are plausible therapeutic targets; while monitoring BAD phosphorylation could be used to predict tumor response to treatments." (PMID 19593445, 2009). "By increasing histone acetylation, martinostat can restore pro-apoptotic factors (e.g., BAD and BIK) and tumor suppressors (e.g., PTEN), suppress pro-survival genes, and restore critical pathways." (PMID 40671124, 2025). "AMPK (CAMKK2, CREBs, PPP2R5A/B, PPP2RC/D) and cAMP (BAD, PLN) pathways regulate energy balance and induce autophagy and apoptosis, inhibiting tumour cell growth." (PMID 41007296, 2025). "Accordingly, we found that apoptotic molecules downstream of T cell–mediated tumor killing were increased post-sotigalimab, including CASP3 and BID and the proapoptotic factor BAD." (PMID 38181044, 2024). "Overexpression of miR-9-5p significantly inhibited the proliferation of HCT116 and SW1116 cell lines by targeting the PAK4 kinase and acted as a tumor suppressor by downregulation of BCL-2 and upregulation of BAD." (PMID 39001526, 2024). "Tumor ROIs in BM-LUAD expressed higher expressions of CD14, CD163, GZMA, BCL-6, BAD, BCLXL, 4-1BB, VISTA, and IDO1." (PMID 37061716, 2023). "GSEA of Biocarta pathways identified five up-regulated pathways with FDR < 0.05 in the M3 iSubtype, which were mainly involved in immune system (CTLA4, CSK, TCR) and tumor progression (SPPA, BAD)." (PMID 34944787, 2021). "Knock down of MCL-1 or BCL-XL enhanced tumor cell death whereas over-expression of BCL-XL was protective as was knock down of BAX, BAK and BAD." (PMID 32047722, 2020).
tumor (continued). "Among them, 6 genes including BCL2, BCL2L11, BAD, CASP7, CASP9, and CYCS expression reduced in tumor tissue compared to normal according to meta-analysis studies and RNA-seq TCGA data." (PMID 33292233, 2020). "In conclusion, our study suggests that under ER stress, CHOP activates GOLGA2P10 expression, whereas GOLGA2P10 in turn protects tumor cells from the cytotoxic effect of ER stress by increasing BCL-xL level and enhancing BAD phosphorylation." (PMID 32332695, 2020). "ABT-737 mimics the BH3-domain of pro-apoptotic BAD and interacts with BCL-2, BCL-XL and BCL-W, displacing BH3-only proteins to trigger apoptosis in cell lines and restrict tumour growth in xenograft models." (PMID 29769323, 2018). "MjTX-I exerts selective cytotoxicity against leukemic cell lines, with low toxicity towards non-tumor cells, and induces apoptosis accompanied by caspases activation and downregulation of BCL-2 and upregulation of BAD expression." (PMID 30598659, 2018). "Our lab found that adrenergic signaling increases expression of the antiapoptotic proteins BAD, BCL-2, and MCP-1 in tumors and blocking adrenergic signaling significantly reduces antiapoptotic protein expression and tumor growth." (PMID 29479349, 2018). "Next, a combination of purified TGF-β and TNF-α was used to replace immunosupressive tumour supernatants with similar consequences on CAL-1 cells activation by CpG, thus confirming that TGF-β prevents the down-modulation of BAD-LAMP in activated pDCs." (PMID 29030552, 2017). "BET and MEK inhibitors not only arrested cell growth but also synergistically elicited tumor cell apoptosis, presumably by coordinately regulating apoptosis proteins such as BIM and BAD." (PMID 26575423, 2016). "Taken together, we concluded that BET and MEK inhibitors synergistically elicited tumor cell apoptosis by coordinately regulating apoptosis molecules including BIM and BAD." (PMID 26575423, 2016). "These bidirectional effects on mTOR and BAD in HCC tissues were in agreement with the survival, aggressive, metastatic, and antiapoptotic effects of tumor cells." (PMID 25243186, 2014). "The RT-PCR analysis on H1650 tumor tissue suggested that p38, Phospho-JNK, Bax, BAD, cleaved caspase 3&8 mRNA expressions were significantly increased in BA SD formulations." (PMID 24614362, 2014). "We also found that high level of BAD protein inhibited cell proliferation in H1299, H292, SPC-A1 cell line, and reduced H1299 tumor growth rate in immunocompetent mice." (PMID 23725574, 2013). "Furthermore, levels of apoptosis related proteins in tumor tissues, including Bim, BID, and BAD, were sharply boosted by sh-TBX21 injection." (PMID 41573646, 2025). "At higher concentrations, autophagy and lysosome biogenesis genes, such as SQSTM1/p62, LAMP2, and PINK1, were robustly upregulated along with tumor suppressors, such as PTEN, and pro-apoptotic factors, including BAD and BIK, which reinforce autophagic flux and promote cellular homeostasis." (PMID 40671124, 2025). "Next, we measured the MACC1 protein levels in tumour samples and found that the in vivo treatment of SS-b2 significantly downregulated MACC1 and c-Met expression and Akt protein phosphorylation, while it enhanced the phosphorylation of BAD." (PMID 39544485, 2024). "Therefore, to further confirm our findings on cell survival and death in tumor tissues of PDX mice, we performed immunoblot analyses of phospho-BAD and Bcl-2 in tumors of in p402 mAb- and p40 mAb-treated PDX mice." (PMID 38136341, 2023).
tumor (continued). "In addition, the phosphorylation of the RPS6KA3 substrates (BAD S118, MTOR S1261, SRF S224, etc.), which involved in the regulation of cell differentiation and the inhibition of apoptotic were upregulated in tumor samples." (PMID 37704624, 2023). "In contrast, BAD and BCLXL were the only proteins found to be upregulated in the tumor center." (PMID 37894418, 2023). "In unmatched analyses of n = 43 primary and 11 nodal metastases, our data indicated that tumor cells in nodal metastases had higher levels of Ki-67, PARP, BAD, and cleaved caspase 9, suggesting a role for increased proliferation, DNA repair, and apoptosis within these metastatic cells." (PMID 35651606, 2022). "According to the expression levels and regression coefficients, the downregulated BAX, PWP2, SERTAD1, S1PR4, ZFAND1, NUDT13 and ZNF107 with HR < 1 were considered as tumor suppressors, whereas the MVD, BAD, CPNE7, CPNE7, UTP23 and ZNF124 upregulated with HR > 1 were regarded as oncogenes." (PMID 36685828, 2022). "We also found that B cell related proteins (CD20, BAD, BCL-2, CD27, BIM) were most highly expressed in the stromal compartments while expression of lymphocyte-related markers (CD3, CD8, CD4, Tim-3) were elevated in tumor compartments." (PMID 34838031, 2021). "Taken together, ER stress may upregulate GOLGA2P10 through the PERK/ATF4/CHOP pathway, and the elevated GOLGA2P10 may confer tumor cells with resistance to ER stress-induced apoptosis by increasing the protein level of BCL-xL and the phosphorylation of BAD." (PMID 32332695, 2020). "Increasing expression of BAD enhances apoptosis and has a negative influence on cell proliferation and tumor growth in NSCLC." (PMID 33193633, 2020). "TNBC tumours were enriched for the expression of phosphorylated BAD protein compared to non-TNBC tumours." (PMID 31767884, 2019). "We also show that, compared to non-TNBC cases, TNBC tumours were enriched in the expression of phosphorylated BAD isoforms." (PMID 31767884, 2019). "While BAD:Bcl-XL binding liberates pro-apoptotic Bax/Bak to trigger cell death, this was inconsistent with our observed increased cell/tumor volume and lack of apoptotic markers." (PMID 30635657, 2019). "Another study suggested that increased expression of BAD enhanced apoptosis and had a negative influence on cell proliferation and tumor growth." (PMID 30283401, 2018). "We observed that ER+ BCC acquired the ability to form a tight tumor-like structure in presence of BAd (data not shown)." (PMID 30105032, 2018). "With the exception of BAD knockout mice, which succumb to late onset lymphoma, deficiency in individual BH3-only proteins does not predispose mice to tumour development." (PMID 29769323, 2018). "Worth to note, CNAs of 37 genes were exclusively found in G3 tumours such as WNT7B (4 gains), BAD (3 gains), WEGFB (3 gains) and HDAC2 (3 losses) in respect to 65 CNA genes exclusively presented in G1 tumours, such as GRB2 (5 losses) and FGF21, STAT3, CTNNA3 and DVL3 with 3 losses each." (PMID 28486536, 2017). "Analysis of tumor tissue extracts by western blot analysis showed increased levels of proapoptotic protein, BAX, decreased p-BAD, and increased levels of cleaved caspase 3 and PARP in tumor tissues obtained from mice treated with Ad.EPCR compared to mice treated with PBS or Ad.Con." (PMID 27833109, 2016).